S100A4 (S100 calcium binding protein A4)
Diseases named in the same sentence as S100A4 in open-access papers (continued):
Sharing a sentence is not in itself a finding about the gene and the disease.
rheumatoid arthritis (continued). "S100A4 signaling via TLR4 and activation of NF-κB are required for the production of proinflammatory cytokines by mononuclear cells in the pathogenesis of rheumatoid arthritis." (PMID 28951732, 2017). "For example, S100A4 is involved in autoimmune pancreatitis, S100A11, S100A8 and S100A9 in rheumatoid arthritis, S100A1 in hypoxia-induced inflammatory response in cardiomyocytes, S100A12 in Crohn’s disease, S100A7 and S100A7A in psoriasis, S100A8, S100A9 and S100A12 in systemic lupus erythematosus." (PMID 30018736, 2018). "S100A4 is a potent trigger of inflammatory molecules, such as interleukin (IL)-1, IL-6, tumor necrosis factor (TNF)-a, and matrix metalloproteinases, which are involved in autoimmune disease developments, such as allergies, rheumatoid arthritis, systemic sclerosis, and psoriasis, etc.." (PMID 36361563, 2022).
liver fibrosis (18 papers, 2012 to 2025). "Like in liver fibrosis, the majority of S100A4-expressing stromal cells in HCC are of myeloid origin." (PMID 40078995, 2025). "Studies from mouse models and human liver fibrosis patients indicate that macrophages are the predominant S100A4 expressing population." (PMID 40078995, 2025). "Based on these findings, CD44 seems to contribute to liver fibrosis through a β-catenin-related pathway regulating S100A4 expression in congestive hepatopathy." (PMID 38731968, 2024). "In detail, Cx3cr1+Ccr2+ Mo-macs can be categorized into M1-like macrophages and S100A4-positive macrophages and then further activate hepatic stellate cells (HSCs) to promote liver fibrosis." (PMID 38627387, 2024). "VIM and S100A4 were upregulated in liver fibrosis but downregulated in IPF; we further collected mice fibrotic livers to examine their expression." (PMID 39257588, 2024). "The utilization of specific hairpin RNA to decrease the expression of S100A4 in CD11b‐positive macrophages from mice with liver fibrosis led to a reduction in the expression of α‐SMA and collagen deposition." (PMID 32307910, 2020). "S100A4 has been identified as a key component in the activation of stellated cells in order to promote liver fibrosis." (PMID 33138772, 2020). "S100A4 produced by an inflammatory subpopulation of macrophages in the liver promotes liver fibrosis via activation of hepatic stellate cells." (PMID 30127784, 2018). "We previously found that during liver inflammation, macrophage-derived S100A4 activates collagen synthesis in hepatic stellate cells, promoting liver fibrosis and cancer development." (PMID 29556233, 2018). "In CCl4-induced liver fibrosis, S100a4 expression, which is controlled by CBP/β-catenin, increased in non-parenchymal cells, suggesting that CBP/β-catenin-mediated signals were activated in the liver." (PMID 30308992, 2018). "S100A4 expression is consistently and dramatically upregulated in carbon tetrachloride (CCl4)-induced hepatic fibrosis and functions as a marker of primary biliary cirrhosis." (PMID 23383075, 2013). "By stimulating proinflammatory cascades by inflammatory gene expressing and profibrogenic cytokine releasing including Il1b, Tnf, Lgals3, S100a6, S100a4, S100a11, and S100a10, Mac1 was characterized as one of the profibrotic contributors during the liver fibrosis progression." (PMID 37724132, 2023). "They found serum S100A4 level was higher in CHB patients with liver fibrosis." (PMID 32307910, 2020). "However, it has recently been shown that in IPF, S100a4 confers fibrogenicity also on mesenchymal progenitor cells, and that its expression in kidney and liver fibrosis coincides with the presence of macrophages." (PMID 29910813, 2018). "In vivo treatment with anti-S100a4-shRNA or S100a4-neutralizing antibody in fibrotic mice reduced accumulation of myofibroblasts, suppressed deposition of collagen, and, therefore, ameliorated the development of liver fibrosis." (PMID 29910813, 2018). "S100A4, a member belongs to S100 super family of calcium-binding proteins (CPB), is associated with the onset and progression of fibrosis in many human tissues, such as liver fibrosis, kidney fibrosis, pulmonary fibrosisc, and cardiac fibrosis." (PMID 23383075, 2013). "In fibrotic cardiac tissue, S100A4 is mainly expressed by hematopoietic cells and endothelial cells (Kong, Christia, Saxena, Su and Frangogiannis, 2013), while S100A4 secreted by subpopulation of macrophage activates hepatic stellate cells during liver fibrosis." (PMID 36817136, 2023). "During the progression of liver fibrosis, enhanced expression of CD44 in HSCs was accompanied by an elevation of S100A4, promoting HSC activation and fibrosis." (PMID 38731968, 2024).
liver fibrosis (continued). "S100A4 expression in mouse liver macrophages was shown to be driven by the CX3CR1/Myd88/NF-κβ signaling axis, and targeting this pathway alleviated liver fibrosis in a high-fat diet-driven mouse model of metabolic dysfunction-associated fatty liver disease (MAFLD) in vivo." (PMID 40078995, 2025). "S100A4 is a driver of the fibrotic response in tendon, and S100A6 has a similar role in liver fibrosis, although the role of S100A6 in tendon, if any, is unknown." (PMID 40224957, 2025). "The current study showed that Cx3cr1+Ccr2+ Mo-macs expressed the adaptor Myd88 and activated the transcription of S100A4 via CX3CR1/MyD88/NF-κB signaling pathway, resulting in the activation of HSCs and thereby promoting the progression of inflammation and liver fibrosis." (PMID 38627387, 2024). "Moreover, PRI-724 treatment reduced liver fibrosis and S100a4 expression without affecting serum alanine aminotransferase (ALT) levels, suggesting that the antifibrotic effects of PRI-724 are not due to the reduction of hepatocellular damage." (PMID 30308992, 2018).
breast tumor (17 papers, 2008 to 2025). "There was little effect of RGC on cell proliferation of the MDA-MB-231 cells despite substantial degradation of S100A4 and on the number of mice bearing 4T1 primary breast tumours despite inhibiting completely the formation of lung metastases." (PMID 37509135, 2023). "Focusing on the functional liaison occurring between breast tumor cells and components of the surrounding stroma, we next assessed that S100A4 secreted by TNBC cells upon FGF2 treatment via RAGE endothelial tube formation and migratory responses in CAFs." (PMID 33946884, 2021). "The expression of S100A4 in breast tumour tissues serves a prognostic marker for poor patient survival." (PMID 18718015, 2008). "The involvement of S100A4 is well-documented across various tumors, including breast tumors." (PMID 41225146, 2025). "Moreover, knockdown or silencing of S100A4 expression significantly inhibited breast tumor invasion and metastasis in vivo." (PMID 29069865, 2017). "However, it is surprising that increasing concentrations of RGC above this value inhibit the incidence of invasion/metastasis with decreasing effect; a result which is largely mirrored by the immunohistochemical staining for S100A4 in the spleen, colon and primary breast tumours." (PMID 37509135, 2023). "Moreover, the expression levels of OSX and S100A4 correlated significantly in human breast tumors." (PMID 30450809, 2019). "Each sample includes five channels: S100A4-Opal 520, CK-Opal 570, PDPN-Opal 650, 4′,6-diamidino-2-phenylindole (DAPI) and bright field with 3,506 × 3,506 pixels along XY (see ‘Multichannel breast tumor data’ section in Methods)." (PMID 41073772, 2025). "Recent studies indicated that abnormal expression of S100 proteins – mainly including S100A2, S100A4, and S100A7 – is related to metastasis of breast tumor." (PMID 31244288, 2019). "During breast tumorigenesis and/or progression, several S100 s, including S100A2, S100A4 and S100A7, exhibit altered expression levels based on molecular analysis of breast tumors." (PMID 31795964, 2019). "Most of S100A4+ stromal cells are derived from bone marrow and the recruitment of CD45+ leukocytes and CD3+ T lymphocytes to tumor lesions is clearly reduced in the breast tumor microenvironment." (PMID 29069865, 2017). "To determine whether fibroblasts co-cultured with miR-510-5p overexpressing breast tumor epithelial cells are ‘activated’, we performed qPCR for collagen (COL1A1) and fibroblast specific protein (FSP1/S100A4), genes that are typically used as markers of cancer associated markers or CAFs." (PMID 37822942, 2023). "Moreover, non-bone marrow-derived S100A4+ cells such as fibroblasts are essential for the metastasis of breast tumor cells to the lung." (PMID 29069865, 2017).
metastatic tumors (17 papers, 2005 to 2023). "Expression analysis of the metastatic tumors identified S100a4 as a top candidate gene associated with metastasis." (PMID 31881983, 2019). "We show that high TG2 expressing SW620 cells express low levels of the epithelial marker ZO-1, but increased levels of mesenchymal markers N-cadherin, α-SMA and protein S100A4 which is associated with metastatic disease." (PMID 28223538, 2017). "Next, strong focal staining of S100A4 has been associated with the development of metastatic disease and thereby poor prognosis in muscle-invasive bladder cancer." (PMID 21979422, 2011). "The metastasis associated protein S100A4 is a small calcium binding protein that is associated with metastatic tumors and appears to be a molecular marker for clinical prognosis." (PMID 15900299, 2005). "S100A4 was firstly reported to have an association with metastatic tumor in 1989." (PMID 37026957, 2023). "S100A4 is one of the most studied members of the family as it is frequently overexpressed in metastatic tumors." (PMID 31652274, 2019). "S100-A4 and S100-A6 have attracted significant attention because of their established significance in the progression of metastatic tumors." (PMID 21637840, 2011). "Further, S100a4 and Arsj were among the top overexpressed genes in the metastatic tumors." (PMID 31881983, 2019). "S100A4 was studied extensively and correlated with metastatic disease and poor survival." (PMID 30980596, 2019). "Using Matrigel patterning as a bioassay, we provide the first functional demonstration that overexpression of S100A4, a calcium-binding protein that is frequently overexpressed in metastatic tumors and inhibits NMIIA activity by inducing filament disassembly, effectively reduces cell contractility." (PMID 31652274, 2019). "Furthermore, combining ANXA10 and S100A4 expression was a highly significant predictor of metastatic disease (P<0.00001, log rank test)." (PMID 21979422, 2011). "Indeed, recent clinical trials have revealed that neutralization of S100A4 activity using anti-S100A4 antibodies or a specific small molecule inhibitor could be an effective and efficient way to control the metastatic diseases." (PMID 29069865, 2017). "Epithelial cell nuclear expression of S100A4 strongly correlates with both active EMT and metastatic disease in the oncology literature." (PMID 21970519, 2011). "Although S100A4 is well known in the oncology literature as a marker of metastatic tumor progression, it has not been studied as extensively in autoimmune diseases." (PMID 29065913, 2017). "Furthermore, we improved the prognostic value considerably by combining S100A4 with ANXA10 expression, which resulted in a strong and independent prediction of metastatic disease in patients with muscle-invasive cancer." (PMID 21979422, 2011).
lymph node metastasis (16 papers, 2005 to 2025). "Previously, we identified that the overexpression of S100A4 is associated with lymph node metastasis and poor prognosis in CRC revealed by proteome analysis." (PMID 22200787, 2012). "In addition, an inverse association was found between S100A4 staining and lymph node metastasis (pN status) (p = 0.04)." (PMID 22853000, 2012). "Our previous investigations have demonstrated that the overexpression of S100A4 is associated with lymph node metastasis and poor prognosis in CRC; however, its biological roles in CRC remain unclear." (PMID 22200787, 2012). "S100A4 expression was found to be positively correlated with clinical grade, lymph-node metastasis, and poor patient survival." (PMID 37190117, 2023). "Lymph node metastasis was predicted by several factors, including a tumor size of 5 mm or larger, sclerosis, S100A4 expression, extrathyroidal invasion, cyclin D1 expression, and multifocality." (PMID 38024552, 2023). "Differentiation, TNM stage, distant metastasis, lymph node metastasis, positive S100A4 expression, and serum CA19.9 level were correlated with the overall survival of patients with PC." (PMID 31526392, 2019). "The elevated expression of S100A4 was significantly correlated with lymph node metastasis (P = .045) in CRC." (PMID 29383839, 2018). "In the present study, we also found that S100A4 expression is significantly correlated with lymph node metastasis." (PMID 26903691, 2016). "As expected, in the present meta-analysis, the results suggested a significant association between high S100A4 expression and advanced TNM stage, nodal status, and tumour depth, as well as the presence of lymph node metastasis." (PMID 24188373, 2013). "In the present study, S100A4 protein expression was examined by immunohistochemistry in infiltrating ductal, infiltrating lobular carcinoma and lymph node metastasis and their relation to tumor promotion and progression." (PMID 18771601, 2008). "S100A10, S100A6, S100A4 and IGFBP3 have all been linked to PTC with lymph node metastasis (LNM)." (PMID 40430098, 2025). "There was a significant association between S100A4-negative expression and N0 lymph node metastasis (RR = 2.15, 95% CI = 1.60–2.88, P < 0.00001, fixed effects model)." (PMID 26903691, 2016). "Positive expression of S100A4 protein was observed only in 13.5 % of cases of infiltrating ductal carcinoma node positive while positive expression of S100A4 protein was observed in 35.1% of matched lymph node metastasis." (PMID 18771601, 2008). "Generally speaking, S100A4 could be a marker for poor prognosis and lymph node metastasis of PC." (PMID 26903691, 2016). "Furthermore, S100A4 was implicated in the process of metastasis in PC and strongly linked to neoplasm invasion, metastasis, and unfavorable prognosis in patients, but had no obvious relationship with lymph node metastasis." (PMID 31526392, 2019). "In paired samples, S100A4 protein was expressed in 13.5% of IDC node positive cases and 35.1% of matched lymph node metastasis." (PMID 18771601, 2008). "To this end, we analysed S100A4 transcripts from 10 patients with matched tissues of normal thyroid, PTC and lymph node metastasis by real-time RT–PCR." (PMID 16265347, 2005). "In patients that already suffer from advanced tumor stages, lymph node metastasis or lymph vessel infiltration, S100A4 expression does not impact prognosis." (PMID 35326507, 2022). "Moreover, negative expression of S100A4 was also related to N0 stage for lymph node metastasis (RR = 2.15, 95% CI = 1.60–2.88, P < 0.0001)." (PMID 26903691, 2016).
thyroid cancer (16 papers, 2005 to 2025). "Furthermore, S100A4 was abundantly expressed in thyroid cancers and strongly associated with LNM and poor prognosis." (PMID 32015423, 2020). "Down-regulation of S100A4 by siRNA in BCPAP and ML-1 thyroid cancer cells decreased cell invasion, metastasis, and angiogenesis, whereas S100A4 overexpression by cDNA transfection led to the opposite effect." (PMID 34209679, 2021). "S100A4 is engaged in proliferation and metastasis of thyroid cancers (follicular, papillary, and anaplastic) because it promotes tumor cell migration." (PMID 34575195, 2021). "But also the RNAi-based knock-down of S100A4 directly in thyroid cancer cells reduced VEGF expression, in addition to MMP-9, and thus invasion and angiogenesis." (PMID 27331819, 2016). "This is consistent with a recent report showing that downregulation of S100A4 decreases VEGF expression in thyroid cancer cells." (PMID 25677816, 2015). "We demonstrated previously the S100A4 overexpression in advanced stage of thyroid carcinomas by Northern blot and real-time RT–PCR analysis." (PMID 16265347, 2005). "Similarly, recombinant S100A4 protein at 500 nM binds to RAGE to significantly promote human thyroid cancer cells migration." (PMID 32307910, 2020). "Taken together with our findings of S100A4 overexpression in advanced thyroid tumours, the transgenic mouse model may fit well with human PTC, implicating that S100A4 may enhance thyroid cancer invasion and metastasis in cooperation with c-erbB-2/neu." (PMID 16265347, 2005). "In an early study, we have shown increased S100A4 expression in thyroid carcinoma specimens with advanced disease stage and indicated that it may be a useful prognostic marker for thyroid carcinoma." (PMID 16265347, 2005). "It has been previously reported that the S100 proteins S100A2, S100A4, S100A6, and S100A9 are upregulated in thyroid cancer and that these subfamily members are involved in the progression of cancer in different ways." (PMID 32015423, 2020). "But also newer reports link S100A4-mediated RAGE signaling to an increase in metastatic potential in cancer, like thyroid cancer and melanoma." (PMID 27331819, 2016). "Investigations performed on AUF1-depleted thyroid cancer cell lines revealed a cross-link between AUF1 and CD9, CD82, S100A4 and ENO1." (PMID 21835052, 2011). "Inversely, increased expression of S100A4 and ENO1 was correlated with increased proliferation and metastatic potential of thyroid carcinoma." (PMID 21835052, 2011). "INSL3 could promote tumor growth and angiogenesis in nude mice model of thyroid cancer in a manner that appeared to be related to the action of RXFP2 and the secretion of S100A4 and (pro-) cathepsin-L." (PMID 35178089, 2022). "Although the upregulation of S100A4 in low-avidity tumors was not statistically significant (p = 0.12), this gene was included in the validation list of genes due to its established role in thyroid cancer and its involvement in tumorigenesis across various other cancer types." (PMID 39982585, 2025).